FGFR1 (fibroblast growth factor receptor 1)
Diseases named in the same sentence as FGFR1 in open-access papers (continued):
Sharing a sentence is not in itself a finding about the gene and the disease.
glioblastoma (53 papers, 2012 to 2025). The most malignant astrocytic tumor (WHO grade IV). "FGFR1 expression shows intertumoral heterogeneity and higher FGFR1 expression is associated with a significantly poorer survival in glioblastoma patients." (PMID 37579831, 2023). "Mutations in FGFR1 have been observed in 1.12% of cases, with a prevalence in lung, colon, breast, endometrial adenocarcinoma, and glioblastoma multiforme." (PMID 32962091, 2020). "Glioblastoma exhibits FGFR1 kinase domain gain-of-function mutations, and FGFR1 is abnormally activated in malignant prostate cells." (PMID 22240789, 2012). "Notably, FGFR1 expression is typically elevated in glioblastoma relative to normal brain tissue and has been associated with resistance to radiotherapy." (PMID 40243482, 2025). "Our study reveals new gene candidates linked to FGFR1-mediated glioblastoma invasion." (PMID 37579831, 2023). "High levels of FGFR1 are associated with better overall survival in peripheral nerve sheath sarcomas, while activating mutations in the FGFR1 kinase domain have been found in a subset of glioblastoma patients with poor prognosis." (PMID 33860438, 2021). "Notably, ZEB1 and Twist1 were recently identified as downstream targets of fibroblast growth factor receptor 1 (FGFR1)/forkhead box M1 (FOXM1) in glioblastoma, and their expression is highly associated with resistance to radiotherapy." (PMID 31234336, 2019). "This family member is shown to regulate endocytosis and stability of the FGFR1 in glioblastoma cells." (PMID 40806483, 2025). "A recent study explored the role of Sprouty (SPRY) proteins—key regulators of receptor tyrosine kinase (RTK) signaling—in modulating FGFR1 endocytosis and degradation in glioblastoma." (PMID 40243482, 2025). "ITGA6 can regulate the expression of FGFR1 in glioblastoma stem cells through the ZEB1/YAP1 transcription complex and upregulate the proliferation and stemness of GBMSCs by synergistically interacting with FGFR1." (PMID 39239559, 2024). "FGFR1 has been shown to be a dependent gene when deleted in glioblastoma cells according to the Dependency Map42 and FGFR1 mRNA expression correlates with poor survival in glioblastoma." (PMID 38654040, 2024). "•Genetic ablation of FGFR1 in patient-derived glioblastoma cell lines confirms functional relevance of FGFR1 for glioblastoma cell migration and invasion." (PMID 37579831, 2023). "LncRNA MIR210HG interacted with octamer transcription factor 1, promoting FGFR1 transcription and glioblastoma multiforme progression." (PMID 37993879, 2023). "LncRNA MIR210HG was reported to promote FGFR1 transcription and glioblastoma multiforme progression." (PMID 37993879, 2023). "FGF2‐induced downstream signaling mediated via FGFR1 has been shown to induce glioblastoma radioresistance through its downstream effector PLCγ,36 indicative a potential role of FGFR1 in modulating normal cell radiosensitivity." (PMID 36051984, 2022). "Enhancement or alterations of PDGFRA, EGFR, insulin-like growth factor receptor (IGFR-1), and basic fibroblast growth factor receptor 1 (FGFR1) accounts for 80% of the primary glioblastoma." (PMID 36185622, 2022). "FGFR1 mutation has been detected in several tpyes of cancers, including midline gliomas (18%), glioblastoma and melanoma, whereas FGFR1 fusion is rare." (PMID 35494629, 2022). "FGFR1 induces glioblastoma radioresistance through the PLCγ and HIF-1α pathways, and inhibition of FGFR1 radiosensitizes glioblastoma cells." (PMID 34127812, 2021). "Several studies have reported that FGFR1 and FGFR2 gene amplification, abnormal activation, or single nucleotide polymorphisms (SNPs) have a key role in glioblastoma progression." (PMID 33352931, 2020). "CDK4 and CDK6 activate FOXM1, and FGFR1 appears to be involved in FOXM1 expression since silencing of FGFR1 in glioblastoma cells resulted in downregulation of FOXM1." (PMID 32976773, 2020).
glioblastoma (continued). "Gene expression analysis revealed profound heterogeneity of FGFR1–4 expression in glioblastoma patients." (PMID 33352931, 2020). "α6-integrin and FGFR1 have been previously shown to contribute to maintaining the stem state of glioblastoma cells." (PMID 30909436, 2019). "Surviving after irradiation was significantly diminished in FGFR1-silenced glioblastoma cells, GC1FGFR1(-) and GC2FGFR1(-), compared to control cells." (PMID 30167084, 2018). "We investigate here the involvement of FGFR1 in glioblastoma stem-like cells (GSLC) radioresistance mechanisms." (PMID 30167084, 2018). "SubG1 level was increased in GC1FGFR1(-) and GC2FGFR1(-) compared to control cells by 61% and 75%, respectively strongly suggesting that FGFR1 silencing increased glioblastoma stem-like cell death induced by radiation." (PMID 30167084, 2018). "Other studies described that FGFR1 increased levels is a common feature in different tumor types, such as glioblastoma and cancers of the breast, lung, prostate, bladder, ovarian, colorectal, and HNSCC." (PMID 29792227, 2018). "In consequence, preclinical and then clinical trials should be designed to test the combination of drug specifically blocking FGFR1 with radiotherapy in the treatment of de novo glioblastoma." (PMID 30167084, 2018). "While the mechanism for their co-expression with the ones on cytoband 4p1 is not clear, literature review shows that the gene TACC3 in Module 66 on cytoband 4p16 is known to have a gene fusion with FGFR1 gene in 3 % of glioblastoma multiforme patients." (PMID 27556416, 2016). "The role of FGFR1 in tumor invasion has been studied in many cancers, but whether and how FGFR1 mediates glioblastoma invasion remains to be determined." (PMID 37579831, 2023). "Interestingly, recent data suggest that FGFR1 inhibitors also decrease resistance to radiotherapy, a widespread problem in glioblastoma." (PMID 33860438, 2021). "It is now speculated that N-Cadherin/FGFR1 interactions could constitute a positive feedback loop in glioblastoma cancer stem cells (GSCs) through subsequent induction of N-cadherin and FGFR1 expression." (PMID 33352931, 2020). "Alterations of FGFR1 have been described in the form of somatic mutations, gene fusions, and intragenic tyrosine kinase domain (TKD) duplications both in pediatric low-grade gliomas and glioblastomas." (PMID 31677015, 2020). "However, occasional point mutations and fusion genes involving FGFR1 have been observed in glioblastomas, which is in agreement with FGFR1 being the most abundant fibroblast growth factor receptor in the nervous system." (PMID 29159601, 2018). "The FGFR1 activation/inactivation cycle is thus possibly boosted in cells with a strong bFGF production, although maintaining a sufficient amount of free receptor for binding, as reported, and also observed for chemokine receptors in human glioblastoma TICs." (PMID 28545562, 2017). "Examples of FGFR fusion driven cancers include: 8p11 myeloproliferative syndrome, a rare stem cell disorder, which contains a number of FGFR1 fusions including FGFR1OP-FGFR1, and glioblastoma multiforme with FGFR3-TACC3 fusions which are found in 3–7% of all GBM." (PMID 27627808, 2016). "In this study, we analyzed the effects of SPRY2 on endocytosis and degradation of FGF receptor 1 (FGFR1) using two human glioblastoma (GBM) cell lines with different endogenous SPRY2 levels." (PMID 39682716, 2024). "FGF2 has also been implicated in glioblastoma multiform (GBM), a grade IV HGG, which also frequently overexpresses FGFR1." (PMID 37130917, 2023). "This α6-integrin–FGFR1 crosstalk underscores the importance of the FGFR1 axis in sustaining glioblastoma stem cell properties and supports its relevance as a therapeutic target in GBM." (PMID 41002392, 2025). "This negative feedback mechanism reduces the phosphorylation of Y653 and Y654, thereby inhibiting the FGFR1/AKT/Snail signaling pathway to suppress the proliferation and invasion of glioblastoma (GBM) cells." (PMID 39590377, 2024).
glioblastoma (continued). "Comparative analysis of RNA-sequencing data of FGFR1 and FGFR2 knockdown glioblastoma cells revealed a FGFR1-specific gene regulatory network associated with tumor invasion." (PMID 37579831, 2023). "The fibroblast growth factor receptor 1 (FGFR1) signaling pathway is a known regulator of therapy resistance and cancer stemness in glioblastoma." (PMID 37579831, 2023). "Here, we investigated the distribution and functional relevance of FGFR1 and FGFR2 in human glioblastoma xenograft models." (PMID 37579831, 2023). "In glioblastoma stem cells, ITGA6 and fibroblast growth factor receptor 1 (FGFR1) have a synergistic effect in their development and tumor spheroid growth." (PMID 37444576, 2023). "Silencing FGFR1 or FOXM1 downregulated genes involved in mesenchymal transition such as GLI2, TWIST1, and ZEB1 in glioblastoma stem-like cells." (PMID 30167084, 2018). "•We find that FGFR1 is present on invasive glioblastoma cells, whereas FGFR2 is absent in these cells and only expressed in the tumor mass." (PMID 37579831, 2023). "Loss of FGFR1, but not FGFR2, significantly reduced cell migration in vitro and tumor invasion in human glioblastoma xenografts." (PMID 37579831, 2023). "A whole genome analysis of more than 2662 adult human glioblastoma samples revealed the number of FGFR-aberrations and amplifications as generally sparse, with prevalence of FGFR1 aberrations of 51 in 3068, FGFR2 in 12 of 2662, FGFR3 in 13 of 2887, and FGFR4 in 9 out of 2456 investigated samples." (PMID 35955806, 2022). "Scientific evidence reveals that human glioblastoma is also characterized by oncogenic fusions involving the members of the FGFR3 and FGFR1 tyrosine kinases (TKs) to the transforming acidic coiled-coil (TACC) proteins, in particular TACC3 and TACC1, necessary to promote cell division." (PMID 33352931, 2020). "The glioblastoma database of the Cancer Genome Atlas, (TCGA, n = 539) was used to analyze the correlations between α6-integrin expression and several potential target genes including ZEB1, YAP1, FGFR1, and FOXM1." (PMID 30909436, 2019). "We first showed that FGFR1 in tumor cells is independent of bad prognostic factors of overall survival and time to progression in glioblastoma." (PMID 30167084, 2018). "Considering that FGFR1 regulates GBM differentiated cells radioresistance and the primordial role of FGF2 in GSC maintenance, we investigate here whether FGFR1 may regulate glioblastoma stem-like cells (GSLC) radiosensitivity." (PMID 30167084, 2018). "The analysis of the molecular docking results shows thatthe inhibition of the activity of the FGFR1, VEGFR2, EGFR, and HSP90proteins is probably not the reason for their observed selective cytotoxicactivity on glioblastoma and colorectal cancer." (PMID 38764643, 2024). "We found FGFR1, but not FGFR2, expressed in invasive glioblastoma cells." (PMID 37579831, 2023). "In addition, we searched samples with available RNA for a known fusion gene involving FGFR1, i.e., FGFR1-TACC1, which is known to play an oncogenic role in glioblastomas, but no gene fusions were found in PCCs." (PMID 29159601, 2018).
eosinophilia (49 papers, 2009 to 2026). "This syndrome has since been classified by the WHO as myeloid and lymphoid malignancies associated with eosinophilia and FGFR1 rearrangement (MLN-eo FGFR1)." (PMID 34734169, 2021). "The association of lymphoblastic lymphoma, eosinophilia, and myeloid hyperplasia has been described in disorders with FGFR1 rearrangements." (PMID 23710385, 2013). "The PDGF and FGFR1 pathways were also interesting, since they are associated with eosinophilia." (PMID 30959925, 2019). "Aberrations of FGFR1 genes are also commonly associated with MPNs with eosinophilia." (PMID 22356850, 2012). "Both the World Health Organization (WHO) and the International Consensus Classification (ICC) have updated the former category of “Myeloid/Lymphoid Neoplasms Associated with Eosinophilia and Rearrangement of PDGFRA, PDGFRB, FGFR1, or PCM1::JAK2”." (PMID 41530508, 2026). "Eosinophilia in the peripheral blood was observed in all three cases with disruption of FGFR1 gene regions." (PMID 38457113, 2024). "The third patient (patient 6) was diagnosed with MLN with FGFR1 rearrangement accompanied by eosinophilia." (PMID 38457113, 2024). "Myeloid (and lymphoid) neoplasms with eosinophilia are associated with rearrangement of the tyrosine kinase (TK) genes, namely PDGFRB, PDGFRA, FGFR1, JAK2, FLT3, and ABL1 (excluding BCR-ABL1)." (PMID 39156600, 2024). "While patients with PDGFRA and PDGFRB fusion genes, who are receiving imatinib treatment, generally have a favorable prognosis, the advent of FGFR1 inhibitors offers hope for individuals with clonal eosinophilia and FGFR1 fusion genes." (PMID 39037514, 2024). "For example, most patients with the FIP1L1::PDGFRA fusion gene present with a chronic myeloid neoplasm with eosinophilia; however, mixed lineage presentations are more common in patients with FGFR1 fusions." (PMID 37076693, 2023). "In general, FGFR1 rearrangement patients are characterized by the following characteristics: (i) eosinophilia; (ii) lymphoid involvement; (iii) rapid transformation; and (iv) rearrangement of 8p11 locus." (PMID 35081975, 2022). "The World Health Organization defines MPD with eosinophilia and constitutively activated platelet-derived growth factor receptor-α, or -β, or fibroblast growth factor receptor 1 as a distinct category." (PMID 33672937, 2021). "Clonal eosinophilia is classified into two categories depending on whether there is a molecular rearrangement of the PDGFRA, PDGFRB, or FGFR1 genes, which are responsible for encoding the tyrosine kinase receptors that aid in eosinophil growth." (PMID 39301376, 2024). "EMS(8p11 myeloproliferative syndrome, EMS) is an aggressive hematological neoplasm with/without eosinophilia caused by a rearrangement of the FGFR1 gene at 8p11-12." (PMID 36408177, 2022). "If these translocations are negative, there is peripheral eosinophilia, or there is a history of leukocytosis with eosinophilia, we recommend FISH for ETV6-ABL1, FIP1L1-PDGFRA, PDGFRB, or FGFR1 rearrangements." (PMID 38337573, 2024). "In a next-generation sequencing study, BCR::FGFR1 rearrangement was documented, a diagnosis of myeloid/lymphoid neoplasia with eosinophilia and BCR::FGFR1 rearrangement was made, and hydroxyurea therapy was initiated." (PMID 36698221, 2023). "The frequency of eosinophilia varied significantly depending on the specific fusion gene involved: it was present in 91% of patients with FIP1L1::PDGFRA and 100% with ETV6::ABL1, but only in 43% of those with PDGFRB, FGFR1, or JAK2 fusion genes." (PMID 41530508, 2026). "Fusion genes involving FGFR1 are also known to be genetic driver in some hematologic malignancies with or without eosinophilia." (PMID 38098111, 2023). "In contrast, it was only observed in 13/30 (43%) patients with PDGFRB, FGFR1 or JAK2 fusion genes Absence of eosinophilia was restricted to 9/30 (30%) patients with PDGFRB, FGFR1 and JAK2 fusion genes." (PMID 37454239, 2023).
eosinophilia (continued). "If either PDGFRA, PDGFRB, FGFR1, or JAK2::PCM1 gene rearrangement is identified, the diagnosis should be classified as “myeloid or lymphoid neoplasms with eosinophilia and tyrosine kinase gene fusions”; eosinophilia may be a clue to this alternative diagnosis." (PMID 38067330, 2023). "After ruling out the hypothesis of non−hematologic origin, testing for gene rearrangements associated with clonal eosinophilia, such as BCR::ABL1, PDGFRA, PDGFRB, FGFR1, PCM1::JAK2, and JAK2::V617F, did not yield any definitive clues." (PMID 38992589, 2024). "Lack of eosinophilia was also evident in patients with FGFR1 fusions." (PMID 37454239, 2023). "Nearly 100 different TK fusion genes, involving at least six TK (PDGFRA, PDGFRB, FGFR1, JAK2, ABL1, FLT3), have been identified in distinct MLN with or without eosinophilia." (PMID 39037514, 2024). "To date, more than 70 different TK fusion genes with recurrent involvement of at least six TK (PDGFRA, PDGFRB, FGFR1, JAK2, ABL1, FLT3) have been identified in clinically and morphologically distinct MLN with or without eosinophilia." (PMID 37454239, 2023). "In 81/135 (60%) evaluable patients, hypereosinophilia (>1.5 × 109/l) was observed in 40/44 (91%) FIP1L1::PDGFRA and 7/7 (100%) ETV6::ABL1 positive patients but only in 13/30 (43%) patients with PDGFRB, FGFR1, and JAK2 fusion genes while 9/30 (30%) patients had no eosinophilia." (PMID 37454239, 2023). "In addition, there were 15 cases with eosinophilia that underwent FISH examination using dual-color split probes for the 8p11.2 loci before routine chromosomal analysis, and no case showed disruption of FGFR1 gene regions." (PMID 38457113, 2024).